USP17L18 (ubiquitin specific peptidase 17 like family member 18)
Description:
Deubiquitinating enzyme that removes conjugated ubiquitin from specific proteins to regulate different cellular processes that may include cell proliferation, progression through the cell cycle, apoptosis, cell migration, and the cellular response to viral infection.
Tractability: No criterion of Open Targets' tractability assessment is met for any kind of drug.
Gene: Protein-coding gene on chromosome 4 (9,248,630 to 9,250,222, forward strand). Ensembl gene ENSG00000250844.
Subcellular location: Nucleus; Endoplasmic reticulum
Pathways (Reactome):
Metabolism of proteins: Ub-specific processing proteases
Gene Ontology:
Molecular function: cysteine-type deubiquitinase activity
Biological process: regulation of apoptotic process; protein deubiquitination
Cellular component: endoplasmic reticulum; nucleus
Homologues: Paralogues in human: USP17L11 (99% identical), USP17L20 (99% identical), USP17L19 (99% identical), USP17L22 (99% identical), USP17L17 (99% identical), USP17L24 (99% identical), USP17L25 (99% identical), USP17L26 (99% identical), USP17L27 (99% identical), USP17L28 (99% identical), USP17L29 (99% identical), USP17L30 (99% identical), and 59 more.